KDELR1 (KDEL endoplasmic reticulum protein retention receptor 1)
Description:
Receptor for the C-terminal sequence motif K-D-E-L that is present on endoplasmic reticulum resident proteins and that mediates their recycling from the Golgi back to the endoplasmic reticulum.
Synonyms: ERD2.1; ERD2; HDEL; PM23
Tractability: Antibody: UniProt predicts a signal peptide or a membrane-spanning region. PROTAC: ubiquitination databases record sites on it.
Gene: Protein-coding gene on chromosome 19 (48,382,575 to 48,393,837, reverse strand). Ensembl gene ENSG00000105438.
Subcellular location: Golgi apparatus membrane; Cytoplasmic vesicle, COPI-coated vesicle membrane; Endoplasmic reticulum membrane; Endoplasmic reticulum-Golgi intermediate compartment membrane
Subcellular location (Human Protein Atlas): Golgi apparatus; Cytosol; Vesicles
Pathways (Reactome):
Vesicle-mediated transport: COPI-dependent Golgi-to-ER retrograde traffic; COPI-mediated anterograde transport
Disease: Assembly and Release of Dengue Virus Virions
Gene Ontology:
Molecular function: ER retention sequence binding; protein binding
Biological process: retrograde vesicle-mediated transport, Golgi to endoplasmic reticulum; protein retention in ER lumen
Cellular component: COPI-coated vesicle membrane; endoplasmic reticulum membrane; endoplasmic reticulum-Golgi intermediate compartment; Golgi apparatus; Golgi membrane; endoplasmic reticulum-Golgi intermediate compartment membrane; transport vesicle; cis-Golgi network; endoplasmic reticulum; membrane
Genetic constraint (gnomAD): Loss-of-function variants: 16 observed, 24.8 expected, observed/expected ratio (o/e) 0.65, 90% interval 0.44 to 0.98. The upper end of that interval is the gene's LOEUF score, 0.98, which puts it in group 4 of 6, group 1 being the genes least tolerant of losing a copy. Missense variants: 159 observed, 257.56 expected, observed/expected ratio (o/e) 0.62, 90% interval 0.54 to 0.7. Synonymous variants: 121 observed, 111.53 expected, observed/expected ratio (o/e) 1.08, 90% interval 0.94 to 1.26.
Homologues: Orthologues: mouse Kdelr1 (99% identical), pig KDELR1 (99% identical), guinea pig KDELR1 (99% identical), dog KDELR1 (97% identical), tropical clawed frog kdelr2 (90% identical), macaque KDELR1 (90% identical), rat Kdelr1 (89% identical), Drosophila melanogaster KdelR (75% identical), Caenorhabditis elegans erd-2.2 (67% identical), Caenorhabditis elegans erd-2.1 (66% identical), chimpanzee KDELR1 (61% identical). Paralogues in human: KDELR2 (83% identical), KDELR3 (71% identical).